CD4 (CD4 molecule)
Diseases named in the same sentence as CD4 in open-access papers (continued):
Sharing a sentence is not in itself a finding about the gene and the disease.
colon adenocarcinoma (42 papers, 2011 to 2025). "Our study on colon adenocarcinoma revealed that STC2 expression was also associated with CD4+ T and CD8+ T cells." (PMID 36685853, 2022). "For instance, the immunogenic intestinal bacteria (Helicobacter hepaticus) inhibited tumor growth of colon adenocarcinoma (COAD) by activating CD4+ T cells- and B cells-associated anti-tumor immunity." (PMID 39115879, 2024). "In this study, we found that knockout of PRDX1 robustly suppressed AOM/DSS‐induced colonic adenocarcinoma compared with wild‐type C57BL/6J mice, accompanied by highly infiltrated CD4+/CD8+ T cells and reduced CD163+ tumor‐associated macrophages (TAMs)." (PMID 41306557, 2025). "One of the mechanisms proposed for IL‐11 mediating immune evasion is a suppression of the anti‐tumoural functions of CD4+ Th1 cells, thereby favouring tumour progression in a mouse model for colon adenocarcinoma." (PMID 40673604, 2025). "To determine the IL21-producing cells in mouse tumors, we analyzed public scRNA-seq data of CD4+ T cells in the MC38 colon adenocarcinoma model." (PMID 37546701, 2023). "An investigation in colon adenocarcinoma revealed that down-regulation of Tspan11 gene was positively correlated with infiltration of CD4+ T cells, macrophages, neutrophils and dendritic cells." (PMID 35263365, 2022). "The expression level of PDLIM2 was positively correlated with immune infiltrates, including B cells, CD8+ T cells, CD4+ T cells, neutrophils, macrophages, and dendritic cells in bladder urothelial, kidney renal papillary cell, and colon adenocarcinoma." (PMID 35121770, 2022). "Results from CIBERSORT analysis revealed that the expression profile of Syk was positively correlated with CD4+ memory resting T cell and M2 macrophages in colon adenocarcinoma, and positively correlated with M0 macrophages in rectal adenocarcinoma." (PMID 33979042, 2021). "In conclusion, this study show accumulation of CCR4+CTLA-4hi Treg stably expressing FOXP3 in colon adenocarcinomas, and close contact between Treg and conventional CD4+ and CD8+ T cells." (PMID 22319577, 2012). "Interestingly, we found that EPAS1 copy number variation (CNV) impacted the infiltration levels of B cells, CD8+ T cells, CD4+ T cells, macrophages, neutrophils and dendritic cells in colon adenocarcinoma (COAD) data." (PMID 37994607, 2024). "In a recent study, the high expression of COL11A1 was positively correlated with CD4+T and CD8+T cells, tumor-associated macrophages (TAM), neutrophils and dendritic cells in colon adenocarcinoma, while the function of these immune cells in colon adenocarcinoma TME has not been identified." (PMID 36389832, 2022). "However, stromal CD4+ cell densities in invasive adenocarcinomas of the colon are significantly higher than those found in adenomas, and these cells are even less common in the normal mucosa." (PMID 27441558, 2016). "In colon adenocarcinoma (COAD), FDX1 expression has a strong correlation with tumor immunity, especially CD8+ T cells and CD4+ T cells, and the pathogenesis of COAD." (PMID 39329964, 2024). "Further investigation into NOTCH3 expression in colon adenocarcinoma (COAD) showed significant positive correlations with CD4+ T cells, macrophages, neutrophils, and dendritic cells." (PMID 39130639, 2024). "We also discussed the specific role of CD4+ MTC-related hub genes in colon adenocarcinoma (COAD) and predicted the effectiveness of immunotherapy and potential therapeutic drugs." (PMID 36105107, 2022). "Our purpose was to comprehensively analyze the effect of CD4+ MTC infiltration on the prognosis of colon adenocarcinoma (COAD)." (PMID 36105107, 2022). "Results showed correlations of PCK1 with a cluster of differentiation 4-positive (CD4+) T cells and macrophages, while neutrophils were negatively correlated in colon adenocarcinoma (COAD) and rectal adenocarcinoma (READ) patients." (PMID 36193307, 2022).
colon adenocarcinoma (continued). "Flow cytometer was executed to detect CD4+ and CD8+ T cell immunoinfiltration levels in colon adenocarcinoma (COAD) patients with high FDX1 expression, results of which were completely consistent with TIMER database analysis." (PMID 37984863, 2024). "On day 60 after infection, recipients were subcutaneously engrafted with syngeneic MC38 colon adenocarcinoma cells and tumor-infiltrating P14 CD8+ and SM CD4+ T cells, and TBYS populations were analyzed on days 10, 15 and 20 after tumor engraftment." (PMID 38609488, 2024). "The results enunciated correlation between RFC1 and RFC5 cluster of differentiation CD4 + T cell, macrophages, and neutrophils were correlated in COAD (Colon Adenocarcinoma) and READ (Rectal Adenocarcinoma) patients." (PMID 38504096, 2024). "Study has found that STC2 together with CD4+ T and CD8+ T cells infiltration influenced the prognosis of colon adenocarcinoma, and played a key role in the prediction of tumor patients at the molecular and cellular levels." (PMID 36685853, 2022). "One previous study has identified that the resting memory CD4+ T cells and M0 macrophages were positively correlated with the TMS score in colon adenocarcinoma." (PMID 35721151, 2022). "Results from CIBERSORT revealed that the expression profile of Syk was correlated with the contents of CD4+ memory resting T cell, M2 Macrophage, CD8+ T cells, activated NK cells, and resting mast cells in colon adenocarcinoma." (PMID 33979042, 2021). "LAYN expression was positively correlated with infiltrating levels of CD4+ T and CD8+ T cells, macrophages, neutrophils, and dendritic cells (DCs) in colon adenocarcinoma (COAD) and stomach adenocarcinoma (STAD)." (PMID 30761122, 2019). "Higher levels of its expression correlate with decreased infiltration of CD4+ T cells and increased infiltration of M0 and M2 macrophages (considering colon adenocarcinoma samples regardless of clinical stage)." (PMID 41234433, 2025). "Similar results were also obtained when Ab:env123–139 was expressed in MCA-38 colon adenocarcinoma cells, indicating either lack of env-reactive CD4+ T-cell priming or ineffectiveness of primed T cells to reject these solid tumors." (PMID 32313208, 2021). "It was found that ATP5A1 and ENO1 were positively correlated with the infiltration of CD4+ T lymphocytes in colon adenocarcinoma and a negative correlation between GADPH and PDIA3 with the infiltration of NK cells and CD4+ T lymphocytes in rectal adenocarcinoma, respectively." (PMID 35445138, 2022). "Moreover, a positive relationship was found between BRAP expression and immune infiltrating cells including B cell, CD4 + T cell, CD8 + T cell, dendritic cell, macrophage cell, and neutrophil cell in colon adenocarcinoma (COAD), kidney renal clear cell carcinoma (KIRC), and LIHC." (PMID 33240929, 2020). "Interestingly, there was a strong correlation between DDX10 expression and the number of infiltrating immune cells, including CD4+ T cells, CD8+ T cells and macrophages, in colon adenocarcinoma (COAD), which was analyzed by the TIMER database." (PMID 38023215, 2023).
Sézary syndrome (42 papers, 2009 to 2025). "Sézary syndrome (SS) is an aggressive form of cutaneous T‐cell lymphoma (CTCL) characterized by the presence of circulating malignant CD4+ T cells (Sézary cells) with many complex changes in the genome, transcriptome and epigenome." (PMID 32794659, 2020). "We examined regulation of RUNX3 by TOX in malignant CD4+ cells derived from PMBCs of Sézary syndrome patients." (PMID 31139323, 2019). "Sézary syndrome (SS) is a leukemic variant of cutaneous T cell lymphoma (CTCL), and the neoplastic CD4+ T cells of SS patients undergo intense clonal proliferation." (PMID 29423061, 2018). "After 24 hours of co-culture at a low E:T ratio of 2:1, CD4CAR NK-92 cells eradicated 58% of CD4+ Sézary syndrome cells from patient 1, and 78% of CD4+ T-ALL cells from patient 2 (N=2)." (PMID 29348865, 2017). "Decreased expression of miR-22 was recently reported in several solid cancers and in circulating CD4+ T cells in Sézary syndrome." (PMID 26244872, 2015). "The TCM group consists of pure CD4+ MFs, and its signature is associated with an adverse effect on patient survival, suggesting that some CD4+ MF lesions may share a cellular origin with Sézary syndrome and could require more aggressive treatment." (PMID 35241665, 2022). "MiR-21, an oncogenic miRNA found in most cancers, plays a major role in Sézary disease, where its expression in cancerous CD4 memory T cells is elevated relative to CD4 T cells in healthy patients, and its activity is associated with signal transducer and activator of transcription 3 (STAT3)." (PMID 36613640, 2022). "Importantly this UV signature was observed in CD4 + T-cells isolated from the blood of Sezary syndrome patients suggesting extensive re-circulation of these T-cells through skin and blood." (PMID 33597573, 2021). "Recently, gene expression profiling and additional immunohistochemical studies have suggested that TOX might represent a potential marker for the histological diagnosis of CTCL, being aberrantly expressed in CD4 neoplastic T cells in MF and Sezary syndrome." (PMID 32106280, 2020). "Thus, the situation in T-PLL is different from that of CD4 T cells of patients with Sézary syndrome in which the SAMHD1 promotor is hypermethylated." (PMID 29352181, 2018). "Sézary syndrome (SS) is a rare leukemic variant of cutaneous T-cell lymphoma (CTCL) that is characterized by erythroderma, generalized lymphadenopathy, and the presence of neoplastic CD4+ skin-homing memory T-cells (SS cells) in the skin, lymph nodes, and peripheral blood." (PMID 26376612, 2015). "PD-1 acts as a tumor suppressor in CD4 T cells and PDCD1 alterations, most commonly focal deletions, recur in 10-20% of CTCL, 36% of Sezary syndrome and 26% of ATL." (PMID 36960072, 2023). "Sézary Syndrome (SS) is a rare aggressive epidermotropic cutaneous T-cell lymphoma (CTCL) defined by erythroderma, pruritis, and a circulating atypical CD4 + T-cell clonal population." (PMID 33106625, 2021). "Sézary Syndrome (SS) is a rare and aggressive cutaneous T-cell lymphoma (CTCL) defined by erythroderma with a circulating atypical CD4 + T-cell clone." (PMID 33106625, 2021). "One case (PCTFHL no 5) presented a monoclonal circulating CD4+ T-cell population without immunophenotyping feature of Sezary syndrome." (PMID 37081015, 2023). "To evaluate whether NLRP3 may regulate IL-4 expression in malignant CD4+ T cells, we used the HTB-176 cell line isolated from the peripheral blood of a patient with Sézary syndrome." (PMID 34220814, 2021). "Here, we report a rare case of Sézary syndrome with CD4/CD8 double-negative Sézary cells in the peripheral blood." (PMID 34123441, 2021).
viral hepatitis (42 papers, 2010 to 2025). An acute or chronic inflammation of the liver parenchyma caused by viruses. "The most important prognostic factor was low CD4 count, followed by smoking, viral hepatitis and HIV transmission through heterosexual contact or injection drug use." (PMID 38008809, 2023). "The expression level of PD-1 in CD4+ T cell subsets and CD4+ T cells in patients with chronic viral hepatitis is also substantially different from that in healthy individuals, and its effect is also closely related to CD4+ and CD8+ T cells." (PMID 35321670, 2022). "PWH coinfected with viral hepatitis with higher HIV RNA levels or lower CD4 cell counts or who contracted HIV through injection drug use had higher HCC rates." (PMID 33595662, 2021). "PWH coinfected with viral hepatitis, those with higher HIV RNA levels or lower CD4 cell counts, and those who inject drugs had higher HCC risk." (PMID 33595662, 2021). "Additional work, including longitudinal studies, will be required to better define the role of CD4 CTL in viral hepatitis, as well as the antigen specificity of these CTL." (PMID 28167943, 2017). "Blood specimen was collected to determine alanine aminotransferase (ALT) and aspartate aminotransferase (AST), CD4 count, and viral hepatitis." (PMID 27493798, 2016). "ART-naïve HIV/viral hepatitis co-infected patients from Icona with a CD4 cell count >200/μl and with a known date of prior HIV neg/pos tests and ≥1 plasma sample stored were included in the study." (PMID 24520976, 2014). "Taken together, our findings indicate the relevance of CD4+ T cells for virus control in the liver, also during acute viral hepatitis." (PMID 24466045, 2014). "To address the role of CD4+ T cells in acute viral hepatitis, we infected mice with Lymphocytic Choriomeningitis Virus (LCMV) of the strain WE; LCMV-WE causes acute hepatitis in mice and is cleared from the liver by CD8+ T cells within about two weeks." (PMID 24466045, 2014). "It is widely accepted that CD8+ T cells are the major effector cells that mediate viral clearance from the liver by removal of infected cells; the role of CD4+ T cells in viral hepatitis is less clear." (PMID 24466045, 2014). "In studies of HIV mono-infected patients that exclude viral hepatitis, one study has reported an increased risk of ALT with lower CD4 while another study reported the opposite findings." (PMID 22069454, 2011). "CD4 T-cells are not activated by liver-derived antigen in contrast to CD8 T-cells, possibly explaining why CD4 T-cell help is found infrequently in patients with viral hepatitis and exhaustion of the CD8 T-cell response results, leading to viral persistence." (PMID 21779338, 2011). "There is already sufficient evidence to suggest that treg plays an important promoting role in the pathogenesis of HCC patients with viral hepatitis, especially CD4 + CD25 + Tregs, and immune checkpoint inhibitors (ICIs) targeting these immune cells can have therapeutic effects on HCC21." (PMID 38365931, 2024). "Therefore, despite the fact that further studies are required to more precisely define the role of CD4+ CTL in viral hepatitis, this subset is very likely involved in immune-mediated pathology." (PMID 37965314, 2023). "Indeed, in the cohort of viral hepatitis patients there was a striking correlation between CD4 Perforin expression and aspartate aminotransferase levels that serves as a marker of hepatocyte damage." (PMID 37965314, 2023). "Indeed, CD4+ CTL, defined as Perforin-expressing CD4+ T cells, were detected in chronic viral hepatitis, especially in HDV infection." (PMID 37965314, 2023). "The CD4+CD25+ regulatory T cells (Tregs) and their effector molecule FGL2 play a key role in susceptibility to HBV infection and in regulating the outcome of fulminant viral hepatitis in vivo." (PMID 30419833, 2018). "Relatively little is known about CD4 CTL responses in viral hepatitis." (PMID 28167943, 2017).
viral hepatitis (continued). "Insufficient virus control and protracted viral hepatitis may be consequences of impaired initial CD4+ T-cell help." (PMID 24466045, 2014). "Our results suggest that ineffective CD4+ T-cell help may promote the evolution of acute liver infection towards chronic viral hepatitis." (PMID 24466045, 2014). "Vita and colleagues found significantly higher sCD163 plasma levels in HIV/CMV coinfected compared to HIV monoinfected subjects matched for age, CD4 nadir, HIV infection duration, and viral hepatitis status." (PMID 34193181, 2021). "The CD4 level reduction and haematological change in patients with viral hepatitis has not been fully proven to be specific as this study still found normal values of CD4 cells and hematological parameters in the subjects of this study." (PMID 37545948, 2023). "Thus, numerical impairment of CD4+ T cells in acute LCMV infection seemed to prevent the clearance of LCMV-WE infection and to induce protracted viral hepatitis." (PMID 24466045, 2014). "This sub-population of immunoregulatory T cells suppresses the activation and effector function of CD4+ and CD8+ T cells; thus, activating Tregs by blocking CTLA-4 may further impair the ability of T cells to keep viral hepatitis suppressed." (PMID 25317333, 2014). "CD4 measurement and viral hepatitis testing was not widely available at all clinics, especially early in the ART program (i.e., 2004–2006)." (PMID 23457477, 2013). "Indeed, many data were missing, including baseline CD4 cell count, weight, WHO stage, and viral hepatitis sero-status." (PMID 23457477, 2013). "Although China’s national HIV care program provides free general laboratory tests, CD4 and viral load tests once a year, people living with HIV have to pay for the remaining tests and examinations, such as BMD measurements, additional viral load tests, and serological tests of viral hepatitis." (PMID 34511077, 2021). "The proportion of intrahepatic CD4+ T cells/mm2 in these biopsies were similar to those in healthy controls and patients with alcoholic hepatitis, but significantly lower than in HBV/HCV-induced viral hepatitis where virus-specific infiltration of the liver is a hallmark of disease." (PMID 33013934, 2020). "Furthermore, it should be mentioned that the main reason for reduction in the CD4+ cell is the progress in the HIV disease, and the reduction in the CD4+ cell count due to viral hepatitis may only be proposed when this decrease occurs dramatically and in the first stages of HIV infection." (PMID 37942194, 2023). "While there was not any notable difference in CD57+ CD4+ T cells among those groups, the percentage of CD3+CD8+ T cells was lower in ARLD patients compared to viral hepatitis with HCC." (PMID 39944754, 2024).